TRPV2 (transient receptor potential cation channel subfamily V member 2)
Diseases named in the same sentence as TRPV2 in open-access papers (continued):
Sharing a sentence is not in itself a finding about the gene and the disease.
muscle degeneration (1 paper, 2020). "The inhibition of TRPV2 (transient receptor potential cation channel), which is a principal Ca2+-entry route, leads to a sustained Ca2+ increase and muscle degeneration in two DMD mouse models." (PMID 33208172, 2020).
muscle disorders (1 paper, 2018). "An assay system developed to measure TRPV2 activation by high throughput screening was used to identify several TRPV2 inhibitors that could be used to treat patients with muscle disorders caused by abnormal Ca2+ handling." (PMID 29581825, 2018).
muscular atrophy (1 paper, 2016). The loss of muscle tissue due to inactivity or disease. "Using immunofluoresence, we next evaluated the presence of the purinergic receptor P2X7 and the transient receptor potential cation channel subfamily V member 2 (TRPV2), which have been previously associated with muscular atrophy." (PMID 27229680, 2016).
neuritis (1 paper, 2019). A neuropathy arising from inflammation of one or more nerves. "In vitro, post-transcriptional modifications, mediated by ERK phosphorylation, have been observed in the TRPV2 protein, suggesting that in neuritis, the TRPV2 activation and the resulting intracellular Ca2+ influx can be directly modulated by ERK." (PMID 30845786, 2019).
oral squamous cell carcinoma (1 paper, 2021). "Furthermore, a role for Ca2+ signaling in induction of MMP gene expression has been described in oral squamous cell carcinoma, suggesting that Ca2+ influx via opening of TRPV2 might indeed modulate expression of MMPs and cellular invasion." (PMID 34936030, 2021).
overactive bladder (1 paper, 2024). Symptom of overactive detrusor muscle of the urinary bladder that contracts with abnormally high frequency and urgency. "The observed upregulation of Chrm2 and Trpv2 detected in the bladder following VCR treatment seems to be aligned with this notion as these genes have been described to play a role in bladder contractility and overactive bladder pathology." (PMID 38951167, 2024).
pancreatic cancer (1 paper, 2024). "The rest of the list expands to high expression of TRPV2 (Transient Receptor Potential Vanilloid 2) in cancerous skin cells, RXRB (Retinoid X Receptor Beta) in bone, and PPARG (Peroxisome Proliferator-Activated Receptor Gamma) in pancreatic cancer." (PMID 39766077, 2024).
Pruritus (1 paper, 2023). Pruritus is an itch or a sensation that makes a person want to scratch. "In this review, we discuss the role of TRP channels TRPA1, TRPV1, TRPV2, TRPV3, TRPV4, TRPM8, and TRPC3/4 in acute and chronic pruritus." (PMID 38139833, 2023). "However, little information is available concerning its contribution to itch sensation and there is no concrete evidence yet whether TRPV2 is involved in various itch conditions." (PMID 38139833, 2023).
psoriasis (1 paper, 2022). An autoimmune condition characterized by red, well-delineated plaques with silvery scales that are usually on the extensor surfaces and scalp. "Analysis of skin biopsies revealed that TRPV2 was downregulated in itchy skin regions of psoriasis patients, while FAAH1, TRPV1 and TRPV3 were upregulated." (PMID 36552866, 2022).
reflux esophagitis (1 paper, 2023). "TRPV2 of macrophages may be associated with the progression of reflux esophagitis." (PMID 37404813, 2023). "The present study showed that TRPV2 was also detected on resident macrophages in the mucosa of normal and reflux esophagitis rats." (PMID 37404813, 2023).
systemic lupus erythematosus (1 paper, 2024). An autoimmune multi-organ disease typically associated with vasculopathy and autoantibody production. "Interestingly, the expression level of TRPV2 correlated with the disease progression of patients with systemic lupus erythematosus (SLE)." (PMID 39185403, 2024).
ureteral stone (1 paper, 2024). "Considering that human ureter is the optimal model for ureter pharmacology, Piezo1 and TRPV2 channels may present promising pharmacological targets to improve ureteral stone passage as well as treatment of stent-associated symptoms." (PMID 38989142, 2024).
urinary tract tumors (1 paper, 2022). "TRPV2 channels have many functions, and they may be related to cancer 59,60, particularly urinary tract tumors 61,62." (PMID 35919815, 2022).
uveal melanoma (1 paper, 2023). A melanoma derived from melanocytes of the uveal tract. "In the Cancer Genome Atlas database, TRPM4 and TRPV2 were identified as negative prognostic markers in uveal melanoma." (PMID 37240443, 2023).
cancer (83 papers, 2013 to 2026). A tumor composed of atypical neoplastic, often pleomorphic cells that invade other tissues. "Remarkably, TRPV2 mRNA expression in primary EC biopsies was associated with tumor invasiveness and cancer stage." (PMID 34936030, 2021). "Depending on the type of cancer, different alterations in the TRPV2 gene (i.e., loss, gain, and splicing) were found to exhibit oncogenic capacity linked to a tumor's growth and metastasis." (PMID 33376561, 2020). "The oncogenic activity of TRPV2 in cancer is mainly associated with the deregulation of its expression and/or alteration of its transcription profile." (PMID 33376561, 2020). "TRPV2 has been linked to adrenomedullin-promoted adhesion and migration of prostate (PC-3) and urothelial (T24/83) cancer cells in a mechanism involving TRPV2 translocation to the cell membrane and increased cytoplasmic Ca2+ levels." (PMID 31275168, 2019). "Depending on the type of cancer, loss, gain, and alternative splicing of TRPV2 gene were found to exhibit oncogenic capacity that is associated with solid tumors growth and progression." (PMID 30733502, 2019). "This was reported for UC, in which a loss or reduction of the short TRPV2 variant was observed during cancer progression." (PMID 31083561, 2019). "Genetic approaches are required to advance a causal understanding on the role of TRPV2 in inflammatory immune-mediated diseases and cancer." (PMID 23420671, 2013). "Notably, TRPV2 is implicated in inducing the death of various cancer cell types; however, many studies also indicate that the action of CBD is also mediated by the receptors TRPV1, TRPV4, CB1, CB2, and VDAC1." (PMID 40006844, 2025). "The expression of four DEGs (C2orf40, NOSTRIN, NFX3, and TRPV2) has been associated with normal lung function, but they have no experimental evidence of their deregulation in cancer, or of their association with the acquisition of the hallmarks of cancer." (PMID 36101460, 2022). "Furthermore, enhanced expression of TRPV2 in triple-negative breast cancer, bladder cancer, and esophageal squamous cell carcinoma is linked to cancer progression and poor patient survival." (PMID 32575381, 2020). "In addition, TRPV2 function and expression are linked to cell migration and cancer metastasis." (PMID 36158191, 2022). "Thus, loss or gain of the TRPV2 gene has been associated with cancer growth and progression." (PMID 24709905, 2014). "TRPV2 is the least studied member of the vanilloid TRP subfamily despite its emerging relevance in cancer metastasis, pain, and inflammation." (PMID 41879799, 2026). "Mechanistically, deficient PPARα-mediated lipophagy leads to the accumulation of ether-lipids within cancer cells, which in turn promotes cell mobility via calcium-dependent, TRPV2 channel-mediated cytoskeletal rearrangement." (PMID 40936093, 2025). "The ability of laser-driven TRPV2–PCNH nanoparticles to regulate cancer stemness was evaluated via immunohistochemistry staining of Ki-67 and CD133, which are proliferation and stem cell markers, respectively." (PMID 40548119, 2025). "Overall, this dual‐gating strategy offers a safe and efficient approach for the precise treatment of cancers with high TRPV2 expression and provides new insights into the design and clinical translation of calcium‐overload‐based cancer therapies." (PMID 40013983, 2025). "TRPV2–PCNH suppresses cancer stemness when exposed to NIR irradiation, contributing to intracellular Ca2+ overload that induces apoptosis." (PMID 40548119, 2025). "TRPV2 is expressed in human cancer stem cells and progenitor cells; its overexpression is reported to suppress stemness." (PMID 41397955, 2025).
cancer (continued). "This TRPV2 channel, expressed in various cancer cell lines, plays a crucial role in survival and metastasis signaling pathways." (PMID 40278648, 2025). "Transient receptor potential vanilloid 2 (TRPV2) is relevant for diseases like cancer, cardiac dysfunction, and infection, warranting drug development targeting TRPV2." (PMID 40773831, 2025). "This study demonstrated that ether-lipids accelerate cancer cell mobility through TRPV2 activation and that pathological PPARα downregulation compromised ether-lipid clearance in HCC, posing significant challenges to cancer prognosis." (PMID 40936093, 2025). "TRPV2 contributes to processes such as innate immune responses, cardiac contractility, cancer cell migration, and inflammatory signaling." (PMID 41511297, 2025). "The knockdown of TRPV2 in cancer cells resulted in a significant reduction in both tumor size and weight, indicating a suppressed tumor growth." (PMID 39334351, 2024). "The identification of TCAF1 as a novel genome protection factor and TRPV2 regulator broadens our understanding of its molecular functions and sheds new light on its cancer relevance." (PMID 38816425, 2024). "In tumors, TRPV2 transcripts were also highly expressed in SKCM as compared to 36 other cancer types." (PMID 36744297, 2023). "We previously demonstrated that TRPV2 knockdown enhances the stemness of cancer stem-like cells through increased expression levels of cancer stem cell markers ALDH1, CD133, and CD44." (PMID 37733242, 2023). "The expression of TRPV2 was clearly positively correlated with immune and stromal scores in most cancers, except KIRP, PCPG, THYM, and UCS, in which the correlation between stromal score and TRPV2 was not significant." (PMID 36830651, 2023). "TRPV2 has been shown to play an important role in the progression and metastasis of different forms of cancer." (PMID 36081847, 2022). "For example, TRPA1, TRPC1, TRPV4, TRPV5, and TRPV6 exhibited higher CNV amplification, while TRPV1, TRPV2, TRPV3, and TRPC3 exhibited frequent CNV loss in cancer." (PMID 35614079, 2022). "For example, TRPV5 and TRPV6 were down-regulated in most cancers, while TRPV2 and TRPV3 tend to be up-regulated in most cases." (PMID 35174089, 2022). "Kaplan-Meier survival analysis indicated that the hypermethylation of TRPV1 in LAML and BLCA, TRPV4 in SARC and UCEC, TRPV5 in BLCA, TRPV2 in ACC, and SARC cancers was associated with a poor prognosis in most tumors." (PMID 35174089, 2022). "TRP channels implicated in mechanotransduction mechanisms that regulate cancer cell migration, invasion and metastasis include, among others, TRPC1, TRPC5, TRPM2, TRPM7, TRPM4, TRPV2 and TRPV4." (PMID 36158191, 2022). "In contrast, in other cancer models, a reverse correlation between TRPV2 expression and the tumorigenic aspect of CSCs was observed, where the downregulation of TRPV2 enhanced stem cell function." (PMID 36142596, 2022). "Overexpression of TRPV2 in urothelial-, prostate-, esophageal squamous cell- and hepatocarcinoma tissues, as well as cell lines of the same cancer types, correlates with advanced disease and metastasis." (PMID 34356643, 2021). "Most studies conclude that increased TRPV2 expression and subsequent increased Ca2+ influx in cancer cells enhances their migratory capacity and facilitates disease progression." (PMID 34936030, 2021). "Some Ca2+-permeable channels have been implicated in the enhanced migration of various cancers: TRPC1, TRPM7, TRPM8, TRPV1, TRPV2, TRPV6, STIM1, Ca2+-release activated Ca2+ modulator 1 (Orai1) and some types of VGCCs." (PMID 36046118, 2021). "While in some cancer cell lines TRPV2 seems to have a positive impact on cancer cell migration, the interplay between TRPV2 and RhoA/Rac1 seems to suppress invasion of Fibroblast-like Synoviocytes (FLS cells)." (PMID 34356643, 2021).
cancer (continued). "Recently, it was found that DOX can inhibit the transient receptor potential vanilloid 2 (TRPV2) channel, a member of the extensive family of NSCCs, in cancer cells by permeating into the channel pore, thereby blocking it." (PMID 34884612, 2021). "Several reports showed that TRPV2 is involved in the regulation of cell death or cancer migration/invasion in cancer cells." (PMID 34671260, 2021). "Unfortunately, most studies investigating the expression of TRPV2 in cancer only focus on tumor cells, possibly overlooking an important contribution of the channel in the tumor microenvironment." (PMID 34936030, 2021). "Firstly, we demonstrated a correlation between TRPV2 expression and resistance to cisplatin-induced apoptosis in three GC cancer cell lines." (PMID 34671260, 2021). "Similar to TRPV6 and TRPV2 (poor prognosis with high expression in numerous cancers), high expression of the PM Ca2+ ATPase 2 (PMCA2) conferred resistance to apoptosis and was associated with a poor prognosis." (PMID 36046118, 2021). "TRPV2 channels control multiple processes involved in cancer progression by modulating survival, cell proliferation, angiogenesis, migration, and invasion in different cancer types." (PMID 34834237, 2021). "Results show that TRPV2 expression increased with the malignancy of the cancer tissue and correlated with shorter PFS (p = 0.0224)." (PMID 32751388, 2020). "Though the possibility to use TRPV2 in cancer therapy is still in infancy, TRPV2 represents a novel promising pharmacologic/molecular target, especially in the management of the most aggressive metastatic cancers." (PMID 33376561, 2020). "Overall, these findings validate TRPV2 as a prime candidate for cancer biomarker and future therapeutic target." (PMID 33376561, 2020). "The Transient Receptor Potential Vanilloid type-2 (TRPV2) channel exhibits oncogenicity in different types of cancers." (PMID 33376561, 2020). "NIR irradiation for 90 s following uptake of 50 μg ml−1 of nanoparticles was significantly more cytotoxic to TRPV2 overexpressing cancer cells than normal cells after 48 h." (PMID 32807785, 2020). "The TRPV2 channel has attracted the attention in many deadly cancers as one of several candidate channels that are involved in the proliferation and resistance of tumor cells to apoptotic cell death." (PMID 33376561, 2020). "Considering the in vitro inhibitory effects of laser-induced TRRV2–PCNH on cancer cell stemness, we suggest that TRPV2-targeted phototherapy inhibits re-initiating activities of tumours." (PMID 32807785, 2020). "Regarding TRPV2, its expression and activation by CBD have been associated with deregulation of proliferation, cell differentiation and invasiveness in different cancer cell lines and animal models." (PMID 32751388, 2020). "Immunohistochemistry staining of Ki-67 (proliferation marker) and CD133 (stem cell marker) was performed to obtain molecular evidences for the regulation of cancer stemness by laser-driven TRPV2-PCNH nanoparticles." (PMID 32807785, 2020). "Here, the authors develop photoactive nanocarbon complexes with second near-infrared photothermal ability to target cancer cells overexpressing the receptor TRPV2 and show it to suppress CSCs through dysregulation of the Wnt/β-catenin signalling pathway." (PMID 32807785, 2020). "TRPV2 was reported to be involved in this process in many cellular models such as PC-3 and LNCaP cancer cell lines where it increases their migration properties." (PMID 32668787, 2020). "SKF exhibited more anti-cancer activity than TL likely because of its ability to negatively regulate f-TRPV2 expression, and alter [Ca2+]i homeostasis." (PMID 30733502, 2019). "Transient receptor potential vanilloid 2 (TRPV2) plays a critical role in neuronal development, cardiac function, immunity, and cancer." (PMID 31566564, 2019).